MALAT1 (metastasis associated lung adenocarcinoma transcript 1)
Diseases named in the same sentence as MALAT1 in open-access papers (continued):
Sharing a sentence is not in itself a finding about the gene and the disease.
breast cancer (continued). "Various studies have reported MALAT-1 overexpression in numerous cancers such as esophageal squamous cell carcinoma (ESCC), gastric cancer (GC), non-small cell lung cancer (NSCLC), colorectal cancer (CRC), pancreatic cancer, breast cancer (BC), and hepatocellular carcinoma (HCC)." (PMID 38201661, 2024). "Notably, MALAT1 is one of the key targets at the downstream of the XBP1-HIF1α axis whose expression correlates with aggressive phenotype, and occurrence of metastasis in breast cancer patients through regulating MYC expression." (PMID 37583933, 2023). "The lower number of peaks compared to the breast cancer model may be explained by the lower expression of MALAT1 in non-cancer cells." (PMID 37367050, 2023). "For example, lncRNA LINC00899 suppresses breast cancer progression by inhibiting miR-425, lncRNA ZFAS1 regulates oesophageal squamous cell carcinoma cell malignant behaviours via the miR-124/STAT3 axis and lncRNA MALAT1 promotes GBM proliferation and progression by targeting the miR-199a/ZHX1 axis." (PMID 33832517, 2021). "Importantly, HIF enhances the connection between the MALAT1 promoter and the downstream enhancer in hypoxia; notably, this is only seen in breast cancer cell lines, and not in non-tumorigenic mammary cell lines." (PMID 35011637, 2021). "However, our in vitro cell model shows upregulation of MALAT1 in all subtypes of breast cancer cells compared to non-cancer cells." (PMID 32708561, 2020). "Interestingly, the depletion of Malat1 in a metastasis‐prone transgenic mouse model of breast cancer reduced lung metastases; however, primary tumors were not different in size." (PMID 32392629, 2020). "We show elevated MALAT1 in breast cancer tissues compared to non-cancerous tissues." (PMID 32708561, 2020). "Similar to breast cancer, our literature search uncovered several high ranked lncRNAs that are linked to blood cancers but yet not been added to the LncRNADisease database, such as MIAT, MALAT1, XIST, CRNDE." (PMID 31379598, 2019). "However, correlation between high MALAT1 expression and poor survival for breast cancer patients was not statistically significant." (PMID 30683807, 2019). "It is also not clear whether MALAT1 has the potential to drive tumorigenicity in various subtypes of breast cancer." (PMID 27250026, 2016). "Moreover, the present study elucidated the MALAT1-miR-124-CDK4/E2F1 signaling pathway in breast cancer, which might provide a new approach for tackling breast cancer." (PMID 26918449, 2016). "In our present work, we have found that MALAT1 expression was significantly upregulated in breast cancer tissues compared with the adjacent non-tumor tissues and breast cancer cells, MALAT1-siRNA significantly inhibited cell proliferation after transfection into MCF-7 and MDA-MB-435S cells." (PMID 26918449, 2016). "In addition, MALAT1 and mRNA correlation analysis in Curtis patient data sets identified several EMT genes the mRNA levels of which were potentially correlated with MALAT1 levels in specific breast cancer intrinsic subtypes." (PMID 27250026, 2016). "Thus, we investigated the expression of MALAT1, CDK4 and miR-124 in breast cancer tissues." (PMID 26918449, 2016). "In addition, another study has not found a link between MALAT-1 overexpression TNM grade, lymph node status and tumor size, indicating that high levels of MALAT-1 do not have a major role in the aggressive behavior of breast carcinoma." (PMID 27608009, 2016). "We also explored the non-protein-coding portion of the breast cancer transcriptome, identifying thousands of novel non-coding transcripts and more than three hundred reads corresponding to the non-coding RNA MALAT1, which is highly expressed in many human carcinomas." (PMID 19379481, 2009). "However, the regulatory mechanism and function of MALAT1 in breast cancer are not known." (PMID 34012919, 2021).
breast cancer (continued). "In the breast cancer mice model lacking the promoter of MALAT1 or MALAT1, tumor differentiation and E‐cadherin are increased, whereas lung metastasis is significantly reduced, indicating that MALAT1 may serve as essential factors for tumor cell colonization at distant metastasis sites." (PMID 34977870, 2021). "In addition, although previously published reviews and meta-analyses have reported that MALAT-1 could function as a potential prognostic biomarker in cancers, no studies have focused on its prognostic significance in breast cancer." (PMID 32700729, 2020). "According to the facts that have been previously reported, we speculated that MALAT1 and Her-2 have common downstream signaling pathways (including PI3K-Akt and RAS-MAPK), and could interact with each other to regulate progression of Her-2 positive breast cancer." (PMID 29416769, 2018). "Compared to non-targeting controls, subcutaneous MALAT-1 ASO reduced metastasis and increased cancer cell differentiation in a MMTV-PyMT breast cancer mouse model." (PMID 39912974, 2025). "In addition, a group of researchers detected the serum levels of lncRNAs PVT1, HOTAIR, NEAT1, and MALAT1 from Egyptian breast cancer and fibroadenoma patients, as well as healthy donors, and found that serum PVT1, HOTAIR, and NEAT1 could serve as potential biomarkers for breast cancer." (PMID 38505593, 2024). "Strand-specific detection of MALAT1 and TALAM1 shown that both lncRNAs are significantly upregulated in all breast cancer cell lines tested comparing to the non-tumorigenic cell line." (PMID 31382922, 2019). "Since its discovery, several studies have reported the link of MALAT-1 to other cancers, including gallbladder-, cervical-, non-small cell lung- (NSCLC), colorectal-, and breast cancer." (PMID 27608009, 2016).
non-small cell lung carcinoma (228 papers, 2007 to 2025). A group of at least three distinct histological types of lung cancer, including non-small cell squamous cell carcinoma, adenocarcinoma, and large cell carcinoma. "The metastasis-associated lung adenocarcinoma transcript 1 (MALAT1) was initially identified in early non-small cell lung cancer." (PMID 39898106, 2025). "This is because MALAT1 is associated with metastasis and in non-small cell lung carcinoma, MALAT1 is being considered as a target for anti-metastatic therapy." (PMID 39912983, 2025). "MALAT1 (Metastasis-Associated Lung Adenocarcinoma Transcript 1), a long non-coding RNA encoded on chromosome 11q13.1, was first identified in non-small cell lung cancer (NSCLC) due to its upregulation in highly metastatic tumors." (PMID 40674376, 2025). "LncRNA-Metastasis-associated lung adenocarcinoma transcript 1 (MALAT1), an 8.5-kilobase long non-coding RNA located on chromosome 11q13, has been extensively studied, primarily in the context of non-small cell lung cancer (NSCLC)." (PMID 38075201, 2024). "It received the name metastasis-associated lung adenocarcinoma transcript 1 because initially it was identified as a prognostic marker of poor outcomes in patients with early-stage non-small-cell lung cancer." (PMID 38674413, 2024). "In conclusion, our study reveals overexpress MALAT-1 cause the drug resistance of EGFR-TKIs in non-small cell lung cancer (NSCLC) through the MALAT-1/miR-125/Rab25 axis." (PMID 39196297, 2024). "LncRNA MALAT1 (Metastasis Associated Lung Adenocarcinoma Transcript 1) was firstly identified in non-small cell lung cancer." (PMID 38334963, 2024). "MALAT1 (metastasis associated lung adenocarcinoma transcript-1) is a 7.5-kb long lncRNA that was discovered to be overexpressed in non-small cell lung cancers." (PMID 36923440, 2023). "Metastasis-associated lung adenocarcinoma transcript 1 (MALAT1), which codes an 8.5-kb lncRNA located at chromosome 11q13.1, is a widely studied lncRNA that was first recognized in human non-small cell lung carcinoma." (PMID 37165307, 2023). "We investigated normalized MALAT1 expression in hepatocellular carcinoma and non-small cell lung cancer in tumor (TCGA) and associated healthy tissue biopsies (GTEx)." (PMID 37235843, 2023). "For example, MALAT-1 (Metastasis associated lung adenocarcinoma transcript 1), a lncRNA, which is used to predict metastasis and survival in non-small cell lung cancer, has also been correlated with PCa development and progression." (PMID 37218885, 2023). "The lncRNA metastasis-associated lung adenocarcinoma transcript 1 (MALAT1) is found in early non-small-cell lung cancer (NSCLC) and can predict metastasis and patient prognosis in early NSCLC." (PMID 35794862, 2022). "In non-small cell lung cancer, an inhibitory effect of MALAT1 on the miR-124 level and its association with EMT induction and cancer progression have been shown." (PMID 36362406, 2022). "Metastasis associated in lung adenocarcinoma transcript 1 (MALAT1) lnRNA is originally recognized in non-small-cell lung cancer (NSCLC) primary stages study, so was given that name." (PMID 36229883, 2022). "Regarding lncRNAs, the lncRNA MALAT1 was originally studied in non-small cell lung cancer and was shown to be associated with tumor metastasis." (PMID 35845040, 2022). "In 2003, lncRNA metastasis-associated lung adenocarcinoma transcript 1 (MALAT1) was first discovered in a study on non-small cell lung cancer (NSCLC) and has attracted attention of researchers in recent years." (PMID 35635083, 2022). "The polymorphisms rs3200401 in MALAT1 was associated with the risk of non-small cell lung cancer and lung squamous cell carcinoma in Chinese Northeast Han population." (PMID 35928715, 2022). "For instance, the high expression of MALAT1 is positively correlated with tumor size and lymph node metastasis in patients with non-small cell lung cancer, while is negatively associated with overall survival." (PMID 34761116, 2021).
non-small cell lung carcinoma (continued). "Metastasis-associated lung adenocarcinoma transcript 1 (MALAT-1) is an lncRNA initially shown to become overexpressed in early non-small cell lung carcinoma and was used as a marker for the prognosis of metastasis." (PMID 34604205, 2021). "Mechanism and roles of the metastasis-associated lung adenocarcinoma transcript-1 (MALAT1) in non-small cell lung cancer (NSCLC) progression." (PMID 34778078, 2021). "MALAT1 is an abundantly expressed nuclear lncRNA that was identified as the first lncRNA associated with metastasis and survival in non-small cell lung cancer." (PMID 34769245, 2021). "Metastasis-associated lung adenocarcinoma transcript 1 (Malat1) was initially identified in non-small cell lung cancer (NSCLC) as a prognostic marker." (PMID 34926450, 2021). "Metastasis associated lung adenocarcinoma transcript 1 (MALAT1) was found in metastasis tissues of patients with non-small cell lung cancer and were overexpressed." (PMID 34805228, 2021). "Long noncoding RNA MALAT1 was identified as a factor associated with metastasis of non-small cell lung cancer and regulated gene expression through different mechanism." (PMID 33482814, 2021). "NRXN1 is one of the SFARI genes, while MALAT1 was proven to be a risk gene for various cancers such as non-small cell lung cancer, hepatocellular carcinoma, gastric cancer, and pancreatic cancer." (PMID 33920310, 2021). "The long non-coding RNA metastasis-associated lung adenocarcinoma transcript-1 (MALAT1) was initially found to be overexpressed in early non-small cell lung cancer (NSCLC)." (PMID 34778078, 2021). "Of the pan-AC prognostic lncRNAs, MALAT1 is a well-known oncogene and has been linked to a variety of cancers so far, including non-small cell lung cancer, cervical cancer, tongue squamous cell carcinomas and gastric cancer." (PMID 33318305, 2020). "Metastasis-associated lung adenocarcinoma transcript 1 (MALAT1) is first demonstrated by Ji and colleagues as an oncogene in non-small-cell lung cancer through the promotion of cell metastasis and invasion." (PMID 33344634, 2020). "Long non-coding RNA metastasis-associated lung adenocarcinoma transcript 1 (MALAT1) was first found in non-small cell lung cancer and also found to be upregulated in high-fat diet ApoE−/− mice and patients with unstable angina." (PMID 32082313, 2020). "Metastasis-associated lung adenocarcinoma transcript 1 (MALAT1) is overexpressed in some tumors, including non-small cell lung cancer that metastasizes to the brain by inducing EMT." (PMID 31900168, 2020). "Metastasis associated lung adenocarcinoma transcript-1 (MALAT1) located on chromosome 11q13 was found to be highly expressed and associated with metastasis in non-small cell lung cancer." (PMID 31479414, 2020). "Metastasis-associated lung adenocarcinoma transcript 1 (MALAT1) was first found in non-small cell lung cancer (NSCLC) patients." (PMID 31214490, 2019). "Metastasis-associated lung adenocarcinoma transcript 1 (MALAT1) is an example of lncRNAs that discovered as a prognostic marker of cancer metastasis in non-small cell lung cancer." (PMID 30514825, 2019). "For example, metastasis-associated lung adenocarcinoma transcript 1 (MALAT1) has been identified as a marker for monitoring metastasis progression and predicting survival in non-small-cell lung cancer." (PMID 30617305, 2019). "Metastasis-associated lung adenocarcinoma transcript 1 (MALAT1) is an oncogene associated with tumor invasion in non-small cell lung cancer which is regulated by DNA methylation." (PMID 32099603, 2019). "In patients with early-stage non-small cell lung cancer high levels of MALAT1 predict a high risk of metastatic progression." (PMID 29641489, 2018). "For example, overexpression of MALAT1, i.e. metastasis-associated lung adenocarcinoma transcript 1, is known to be associated with metastasis markers in non-small cell lung cancer and colorectal cancer." (PMID 30281678, 2018).
non-small cell lung carcinoma (continued). "The metastasis associated lung adenocarcinoma transcript 1 (MALAT1), was firstly described as a predictive biomarker for metastasis in the early stage of non-small cell lung cancer and then in other cancers." (PMID 29246026, 2017). "For instance, MALAT1 was found to be highly expressed and associated with metastasis and poor prognosis in many cancer types, including non-small cell lung carcinoma and hepatocellular carcinoma." (PMID 28346506, 2017). "MALAT1 is highly expressed in lung cancer, pancreatic cancer, non-small cell lung cancer, and is closely associated with cancer metastasis in patients with non-small cell lung cancer." (PMID 28738810, 2017). "Metastasis-associated lung adenocarcinoma transcript-1 (MALAT-1)/nuclear enriched abundant transcript 2 (NEAT2) has been described as a regulator of metastasis and motility, and its expression is associated with metastasis in non-small cell lung cancer." (PMID 26989678, 2016). "Our research is focused on MALAT-1, originally identified in non-small cell lung cancer, is a large non-coding RNA that is closely associated with tumor metastasis and regulates the expression of various metastasis-associated genes." (PMID 27227769, 2016). "Metastasis associated lung adenocarcinoma transcript 1 (MALAT1) was used to predict metastasis and survival in patients with early-stage non-small cell lung cancer." (PMID 26110379, 2015). "MALAT-1 was the first lncRNA that was found to be associated with high metastatic potential and poor patient prognosis in non-small-cell lung cancer patients." (PMID 26448942, 2015). "Several studies suggested that high MALAT1 expression is associated with poor prognosis in non-small cell lung cancer (NSCLC), whose elevated expression is also associated with cellular hyper-proliferation." (PMID 26363020, 2015). "For example, the cancer-related lncRNA, MALAT-1 (Metastasis-Associated in Lung Adenocarcinoma Transcript 1), was identified by subtractive hybridization during screening for early non-small cell lung cancer with metastasis." (PMID 25885227, 2015). "The first study that linked MALAT1 to cancer was in non-small cell lung cancer (NSCLC) patients in 2003." (PMID 24932303, 2014). "Metastasis-associated lung adenocarcinoma transcript 1 (MALAT1) is a long non-coding RNA originally identified in non-small cell lung cancer." (PMID 24932303, 2014). "Examples include the increased expression of HOTAIR in metastatic breast cancer, ANRIL-induced silencing of p15 in leukemia, and MALAT1 association with metastasis in non-small cell lung cancer." (PMID 25116943, 2014). "The long noncoding RNA MALAT1 (metastasis-associated lung adenocarcinoma transcript 1) is described as a potential biomarker for NSCLC (non-small cell lung cancer)." (PMID 24313945, 2013). "For example, the cancer-related lncRNA, metastasis-associated lung adenocarcinoma transcript 1 (MALAT-1), was identified by subtractive hybridization during screening for early non-small cell lung cancer with metastasis." (PMID 24222893, 2013). "Previously, a transcript in the NEAT2 region was partially described in a screen for genes overexpressed in metastatic non-small-cell lung cancer and given the name Metastasis Associated in Lung Adenocarcinoma Transcript 1 (MALAT-1)." (PMID 17270048, 2007). "MALAT1 (Metastasis Associated Lung Adenocarcinoma Transcript 1) is a broadly studied lncRNA with a length of ∼8000 nt, which was firstly founded as a prognostic marker in non-small cell lung cancer." (PMID 39479021, 2024). "MALAT1 (Metastasis associated in lung adenocarcinoma transcript 1) is located on chromosome 11q13 with an 8.5 kb lncRNA, which was initially discovered in early-stage non-small cell lung cancer." (PMID 35397764, 2022). "However, it has been revealed that genotypes C/T and C/T +T/T in MALAT1 rs3200401 were related to reduce the risk of death in non-small-cell lung cancer." (PMID 35517413, 2022).